FLT3 (fms related receptor tyrosine kinase 3)
Diseases named in the same sentence as FLT3 in open-access papers (continued):
Sharing a sentence is not in itself a finding about the gene and the disease.
lymphoma (21 papers, 2012 to 2025). A malignant (clonal) proliferation of B- lymphocytes or T- lymphocytes which involves the lymph nodes, bone marrow and/or extranodal sites. "Primary data from this phase I, first-in-human study investigating the safety, tolerability, and preliminary efficacy of SYK/FLT3 inhibitor mivavotinib, conducted in patients with advanced solid tumors or lymphoma malignancies, were previously reported." (PMID 36702329, 2023). "Preclinical studies in a murine lymphoma model have investigated the Fms-like tyrosine kinase 3 (Flt3)-ligand with radiotherapy and poly(ICLC)." (PMID 36106115, 2022). "Additionally, FLT3-D835Y mice develop a broader variability of disease phenotypes (MPNs, lymphomas, histocytic sarcomas, and hemangiosarcomas) compared to FLT3-ITD mice." (PMID 34944812, 2021). "The novel SYK and FLT3 inhibitor TAK-659 prevents the enlargement of spleen and tumor development in a mouse model of EBV-associated lymphoma by counteracting the activation of cellular kinase SYK through the viral LMP2A gene by inducing cell death in tumor cells but not in nontumor cells." (PMID 30135222, 2018). "Furthermore, FMS-like tyrosine kinase 3 (FLT3) and isocitrate dehydrogenase inhibitors have been proven to work as successful therapies alone and in conjunction with other modalities in a percentage of lymphoma patients." (PMID 37366925, 2023).
gastrointestinal stromal tumor (16 papers, 2010 to 2025). "Unlike other AML treatments, quizartinib has not been studied extensively due to its limited efficacy on solid tumors, which harbor few genetic mutations in FLT3, with the exception of gastrointestinal stromal tumors (GISTs), which harbor gain-of-function mutations in the KIT receptor." (PMID 31554189, 2019). "Later on, the indolinone-derivative sunitinib with a broad spectrum activity targeting VEGFR, PDGFR, FGFR, KIT, and FLT3, was approved for the treatment of renal cell carcinoma, as well as second-line therapy in the imatinib-resistant gastrointestinal stromal tumor (GIST)." (PMID 29455673, 2018). "For example, Sorafenib, a VEGFR, PDGFR, KIT, FLT3, and RAF inhibitor, was recently evaluated in clinical trials for its effectiveness against gastrointestinal stromal tumors." (PMID 29132432, 2017). "Sunitinib is an orally bioavailable multityrosine kinase inhibitor that blocks VEGFR1-3, Flt-3, PDGFR-α, PDGFR-β, c-Kit, CSF-1R, and RET with proven antitumor activity in renal cell carcinoma and imatinib-resistant or -intolerant gastrointestinal stromal tumor (GIST)." (PMID 21961001, 2012). "For example, imatinib and sunitinib, which are used on gastrointestinal stromal tumours (GISTs), simultaneously interrupt BCR-ABL, KIT, and PDGFR tyrosine kinase pathways, promoting cell cycle arrest; sorafenib inhibits the VEGFR, PDGFR, KIT, FLT3, and RAF pathways in late-stage kidney cancer." (PMID 26312766, 2015). "Furthermore we evaluated the gene expression of KIT as well as the alternative RTK FLT3, CSF1-R, PDGFRB, AXL and MET in mutated and non-mutated gastrointestinal stromal tumors by qPCR using the identified reference genes." (PMID 21171987, 2010). "Sunitinib (SU011248), a small molecule inhibitor of class III and class IV receptor tyrosine kinases, including VEGFR1-3, PDGFR-α/β, c-Kit, Flt3, and RET, is currently approved for the treatment of renal cell carcinoma (RCC) and imatinib-refractory gastrointestinal stromal tumors (GIST)." (PMID 28384190, 2017). "The compound’s selective inhibition of PDGFR, with no activity on FLT3, highlights its potential as a targeted therapy for PDGFR-driven cancers: such as non-small cell lung cancers, gastrointestinal stromal tumors, and ovarian cancers." (PMID 41286812, 2025).
hepatocellular carcinoma (16 papers, 2013 to 2025). A malignant tumor that arises from hepatocytes. "Sorafenib is a first-generation multi-target FLT3 tyrosine kinase inhibitor that has been used since 2007 in oncology, for treatment of advanced hepatocellular carcinoma and renal carcinoma." (PMID 37007116, 2023). "Sorafenib targets VEGFR-2 and -3, PDGFR-b, Flt-3, and c-Kit and is used in the treatment of hepatocellular carcinoma and renal cell carcinoma." (PMID 38069386, 2023). "We co-cultured MV4-11 cells (a FLT3-ITD mutation AML cell line) with BMSCs and tested the sensitivity of sorafenib, a TKI proved by Food and Drug Administration for hepatocellular carcinoma and renal cell carcinoma." (PMID 27248172, 2016). "However, in this case, as the patient lacked FLT3 mutations and considering the available combinational data on sorafenib and immunotherapy for hepatocellular carcinoma (HCC) sorafenib was deemed the more suitable choice." (PMID 39011472, 2024). "We have selected several genes (SPP1, FLT3, KIF18A, SOCS2) of unclear significance in hepatocellular carcinoma." (PMID 37346073, 2023).
leukocytosis (16 papers, 2011 to 2024). "FLT3–ITD-positive AML cases (n = 579) were associated with higher leukocytosis (median 78.8 × 109/L vs. 28.3 × 109/L, p < 0.001) and higher bone marrow blasts (median 61.3% vs. 36.8% p < 0.001) at diagnosis." (PMID 36497281, 2022). "The presence of ITD mutations in the FLT3 gene is related to raised blast counts and leukocytosis." (PMID 37892567, 2023). "However, FLT3/ITD mutations are frequently accompanied with leukocytosis, high percentage of blasts in bone marrow (BM), and increased the risk of treatment failure in AML patients." (PMID 34711001, 2021). "It is interesting that the phenotype caused by expression of mutated FLT3 in mouse models highly resembles the one observed in mice with high levels of FL; i.e., leukocytosis, splenomegaly, anemia, expansion of DC and myeloid progenitors and reduced B cell generation." (PMID 28538663, 2017). "From these findings we may hypothesize that the presence of the FLT3-ITD mutation might be more important for a dismal outcome than leukocytosis alone or a microgranular morphology." (PMID 22742960, 2012). "FLT3-ITD is closely associated with an unfavorable prognosis, leukocytosis, high white blood cell count, increased risk of relapse, and shortened overall survival." (PMID 38322112, 2024). "Our data also showed a relationship between the FLT3 mutation and BCR3 isoform, but in our data, WBCmax showing progressive leukocytosis was the most important independent factor for predicting early complications and long-term survival outcomes." (PMID 31417123, 2019). "The well-known association between leukocytosis and FLT3-ITD in APL is further expanded upon in this study by the novel revelation of the WBC’s relationship with the ITD allelic burden, with every 1% increase in allelic burden equating to a 0.6 × 109/L increase in WBC." (PMID 33800974, 2021). "Groups with higher FLT3–ITD ARs were more frequently female (p = 0.008), had higher leukocytosis (p < 0.001), and more frequently showed the co-occurrence of mutated NPM1 (p < 0.001)." (PMID 36497281, 2022). "We found a strong correlation between FLT3-ITD and leukocytosis in APL, suggesting a WBC cutoff of ≥25 × 109/L as an indicator for considering testing for FLT3-ITD in APL." (PMID 33800974, 2021). "As expected, FLtg mice exhibit a tremendous expansion of Flt3+ cells, including myeloid cells, DC, MPP, CMP, Granulocyte-Macrophage Progenitors (GMP), CLP and EPLM progenitors, resulting in leukocytosis in the blood and splenomegaly." (PMID 28538663, 2017). "Cases with FLT3-ITD presented a microgranular morphology, PB leukocytosis and expression of HLA-DR, CD34 and CD11b." (PMID 22742960, 2012). "Patients with MLN with FLT3 rearrangement often present with leukocytosis with or without eosinophilia and monocytosis and frequently show extramedullary involvement." (PMID 38611061, 2024). "FLT3-ITD AML cells are characterized by their high proliferation rate and leukocytosis in patients." (PMID 27387666, 2016). "CR rate was significantly influenced by leukocytosis with a cut-off at WBC>30 G/L (95% CI, 0.14-0.68, OR, 0.3, p=0.01) but not by age, CEBPA, NPM1 or FLT3-ITD mutations." (PMID 22081665, 2011). "Moreover, CXCR4 is a prognostic marker that is independent of other classical factors such as age, leukocytosis, FLT3 mutant, and extramedullary infiltration." (PMID 31518054, 2019). "As for the FLT3-TKD mutation, the associations are less clear and more dependent on the other cytogenetic and molecular aberrations, and the presence of leukocytosis may be observed; however, its prominence is not as significant as in instances with ITD mutations." (PMID 37892567, 2023).
multiple myeloma (16 papers, 2013 to 2025). "Anti-myeloma activity of FLT3 inhibitors (midostaurin, gilteritinib) was tested in vitro on MM cell lines and primary MM cells by 3H-tymidine incorporation assays or flow cytometry." (PMID 32825035, 2020). "According to this idea, we demonstrate in our study that FLT3 inhibitors (i.e., midostaurin and gilteritinib) exert promising anti-myeloma activity in vitro." (PMID 32825035, 2020). "The functional relevance of FLT3 expression was corroborated by demonstrating the in vitro anti-myeloma activity of FLT3 inhibitors on FLT3-positive MM cell lines and primary MM cells." (PMID 32825035, 2020). "Midostaurin (PKC412), an oral multi-kinase inhibitor of PKCalpha, beta, and gamma isoforms and AKT, as well as of the TK receptors PDGFR, VEGFR, and FLT3, is known to induce apoptosis in human myeloma cells (." (PMID 27655636, 2016). "Another stress inducer is the proteasome inhibitor Bortezomib (Btz), the first one approved by the Food and Drug Administration, for treating mantle cell lymphoma and multiple myeloma, and we demonstrated that used in combination with RA and ATO efficiently causes FLT3-ITD + AML cell death." (PMID 38909325, 2024). "In addition, FLT3 gene expression levels were determined by real-time PCR in myeloma cell lines and AML cell line." (PMID 32825035, 2020). "Additionally, the use of selinexor has recently received accelerated FDA approval in patients with relapsed multiple myeloma, making it immediately available for clinical combination with a FLT3 inhibitor." (PMID 32545904, 2020). "We evaluated the expression of FLT3 tyrosine kinase receptor (FLT3, CD135) in myeloma cells as a possible clonal driver." (PMID 32825035, 2020). "Our study could be extrapolated to other drug-resistant diseases like Flt3-ITD AML, multiple myeloma or solid tumors that acquire oncogene independent drug-insensitivity." (PMID 34120146, 2021). "FLT3-internal tandem duplication (FLT3-ITD, AML), FGFR3K650E (multiple myeloma), PDGFRAY288C or V561D (carcinomas/GIST), and a splice variant of TRKA (TRKAIII, neuroblastoma) are found in early secretory compartments, and EGFRL858R/T790M, GP130⊿YY, and CSF3RT618I mislocalize to endosomes." (PMID 31484543, 2019).
Myelodysplasia (16 papers, 2013 to 2026). Clonal hematopoietic stem cell disorders characterized by dysplasia (ineffective production) in one or more hematopoietic cell lineages, leading to anemia and cytopenia. "AML-related SS is often associated with cytogenetic abnormalities such as -5/del(5q), FLT3 mutations, and features of myelodysplasia-related AML." (PMID 40869568, 2025). "However, the presence of myelodysplasia-related mutations in NPM1-mutated/FLT3-ITD-negative patients portended worse outcome, which placed these patients firmly in the 2022 ELN intermediate, not favorable, group." (PMID 36823396, 2023). "Consequently, we compared outcome of the NPM1-mutated/FLT3-ITD-negative patients who carried myelodysplasia-related mutations with outcome of patients included in the 2022 ELN intermediate group." (PMID 36823396, 2023). "Smear showed peripheral blasts, and bone marrow biopsy revealed myelodysplasia-related AML with complex karyotype on chromosomal analysis and presence of FLT3 D835 mutation on FLT3 and next-generation sequencing (NGS) analysis." (PMID 41281130, 2025). "All these patients had mutated NPM1 with a low allele ratio of FLT3-ITD, three patients also had one or more myelodysplasia-related gene mutations, and one patient also had a biallelic but non-bZIP CEBPα mutation." (PMID 38609396, 2024). "For example, midostaurin is added to target FLT3-ITD/TKD mutations; gemtuzumab ozogamicin (GO) is added to target the high expression of CD33; and CPX351 is added to target AML with myelodysplasia-related changes (AML-MRC)." (PMID 36181538, 2022). "FLT3-ITD, NPM1, and IDH1/2 were the most mutated genes, while also high proportion of ASXL1 and RUNX1 mutations could be detected, indicating the high proportion of myelodysplasia-related AML." (PMID 39453477, 2025). "CPX did not provide a survival benefit in patients with myelodysplasia (MDS)-related mutations and was associated with poorer survival in patients with NPM1 (HR, 2.83) and FLT3 mutations (HR, 2.14)." (PMID 41237344, 2026). "Among favorable-risk patients, myelodysplasia-related mutations did not affect patients with CEBPAbZIP mutations or core-binding factor AML, but changed risk assignment of NPM1-mutated/FLT3-ITD-negative patients to intermediate." (PMID 36823396, 2023).
renal cell carcinoma (16 papers, 2010 to 2023). "After clinical progression, he was treated with sorafenib, a multiprotein kinase inhibitor more commonly used in the treatment of hepatocellular and renal cell carcinoma due to its off target FLT3 inhibition." (PMID 35571528, 2022). "The orally available anti-angiogenic TKI, sorafenib is a multi-targeted inhibitor of raf-kinase, VEGFR1, VEGFR2, VEGFR3, PDGFR-β, Flt3 and c-kit, which has been approved in the treatment of both advanced renal cell carcinoma and hepatocelullar carcinoma." (PMID 20010948, 2010). "For example, Sorafenib and Sunitinib are two drugs that have been approved for the therapeutic management of advanced‐stage renal cell cancer, which can depress the development of renal cell cancer by inhibiting VEGFR, PDGFR, and FLT3 expression levels." (PMID 36728187, 2023). "Sunitinib, targeting VEGFR1-3, PDGFR-α/β, KIT, FLT-3, colony-stimulating factor receptor Type 1 (CSF-1R), RET, for gastrointestinal stromal and pancreatic cancers and renal cell carcinoma." (PMID 34956857, 2021). "Sorafenib, targeting VEGFR1-3, PDGFR-β, FLT-3, c-KIT, RAF kinases, for hepatocellular and renal cell carcinomas and thyroid cancer." (PMID 34956857, 2021).
glioblastoma (15 papers, 2015 to 2026). The most malignant astrocytic tumor (WHO grade IV). "For this reason, its silencing in glioblastoma cells causes a downregulation of genes related to tumor progression and DNA repair mechanisms, including PI3K/AKT, Insulin-like Growth Factor 1(IGF1), Fms-like Tyrosine kinase 3 (FLT3), Platelet-Derived Growth Factor (PDGF), and MAPK." (PMID 39769286, 2024). "Its inhibition synergizes with conventional chemotherapy (e.g., resensitizing FLT3-ITD+ AML to cytarabine) and emerging immunotherapies (e.g., enhancing CAR-T infiltration in glioblastoma by normalizing vasculature)." (PMID 41486146, 2026). "ATF4-PHGDH targeting sensitizes FLT3-ITD+ AML to cytarabine, overcomes FGFR1/glutaminase inhibitor resistance, and normalizes vasculature to potentiate CAR-T efficacy in glioblastoma." (PMID 41486146, 2026). "Pacritinib is a JAK2/FLT3 inhibitor with IRAK1 inhibiting capabilities, presently under clinical investigation for myelofibrosis and glioblastoma." (PMID 34355696, 2021). "A novel multikinase inhibitor of MET, VERFR1, AXL, TIE2, KIT, FLT3, and RET, called cabozantinib (also known as XL184), inhibits the growth, metastasis, and angiogenesis in pancreatic cancer and glioblastoma, and reduces resistance to gemcitabine." (PMID 26225770, 2015).
systemic mastocytosis (14 papers, 2013 to 2025). Systemic mastocytosis (SM) comprises a heterogeneous group of rare acquired and chronic hematological malignancies that are related to an abnormal proliferation of mast cells in tissue, including bone marrow, with or without skin involvement. "Based on the results of clinical trials, the FDA approved its indications in FLT3-mutated AML and KIT-mutated systemic mastocytosis patients in 2017." (PMID 36230769, 2022). "Midostaurin, which is active in advanced systemic mastocytosis with KITD816V mutations, was recently found to significantly increase overall survival in a phase-3 clinical trial on AML patients with FLT3 mutations." (PMID 31311917, 2019). "In the present study, we found that midostaurin, a clinically available therapeutic agent against FLT3-mutated AML and KIT-mutated systemic mastocytosis, may be repositioned to an enhancer for anti-PD-1 against colon cancer." (PMID 36230769, 2022). "Last year we saw the first positive phase 3 results with a FLT3 inhibitor (the RATIFY trial with the rather unspecific midostaurin which is currently undergoing Food and Drug Administration (FDA) priority review for FLT3 mutated AML and systemic mastocytosis)." (PMID 28386295, 2017). "Midostaurin, an inhibitor of several Type III tyrosine kinase receptors, is approved for newly diagnosed adult patients with FLT3-mutated AML and advanced systemic mastocytosis (SM), especially MCL with KIT D816 mutations." (PMID 41199910, 2025). "Midostaurin was approved by the US FDA and the European Medicines Agency for both newly diagnosed FLT3-mutated AML and advanced systemic mastocytosis (SM) driven by KIT mutation." (PMID 35211416, 2022).
chronic myelomonocytic leukemia (13 papers, 2013 to 2026). A myelodysplastic/myeloproliferative neoplasm which is characterized by persistent monocytosis, absence of a Philadelphia chromosome and BCR/ABL fusion gene, fewer than 20 percent blasts in the bone marrow and blood, myelodysplasia, and absence of PDGFRA or PDGFRB rearrangement. "A bone marrow biopsy demonstrated: 15 % blasts with chronic myelomonocytic leukemia - 2 (CMML-2) with FLT3, DNMT3A, and KMT2A mutations." (PMID 39691506, 2025). "The current study attempts to demonstrate the existence of double minute chromosomes via FLT3 gene amplification in a patient diagnosed with chronic myelomonocytic leukemia (CMML)." (PMID 34194582, 2021). "Four years post-transplant, he developed chronic myelomonocytic leukemia (CMML-1) characterized by re-emergence of driver mutations without FLT3-ITD, marked loss of donor myeloid chimerism, preserved donor T-cell chimerism, and sustained renal allograft function." (PMID 42231121, 2026). "Here, to our best knowledge, we present the first case of amplification encompassing the FLT3 gene acting as dmin in a patient with chronic myelomonocytic leukemia (CMML)." (PMID 34194582, 2021). "While drugs targeting activating mutations like FLT3 and alterations key to leukemogenesis (e.g., menin and aberrant IDH enzymes) offer important progress in precision approaches to AML, the mutations more often found in MDS or chronic myelomonocytic leukemia (CMML) are ripe for targeting." (PMID 39997326, 2025).